METTL3 (methyltransferase 3, N6-adenosine-methyltransferase complex catalytic subunit)
Diseases named in the same sentence as METTL3 in open-access papers (continued):
Sharing a sentence is not in itself a finding about the gene and the disease.
glioblastoma (continued). "For instance, while elevated METTL3 levels have been linked to the proliferation and metastasis of AML cells, they have also been shown to inhibit the progression of glioblastoma by modulating mRNA stability and translation in a context-dependent manner." (PMID 39416774, 2024). "Specifically, the upregulation of the pro-apoptotic variant BCL-XS was observed in METTL3-silenced cells, while the anti-apoptotic variant BCL-XL showed increased expression in control glioblastoma cells." (PMID 38398118, 2024). "Conversely, overexpression of METTL3 can elevate m6A levels in glioblastoma stem cells and suppress their growth." (PMID 38778403, 2024). "For example, the m6A methyltransferase METTL3 mediates the expression of a histone modifier EZH2 in an m6A‐dependent manner under temozolomide treatment in glioblastoma." (PMID 38773866, 2024). "METTL3’s oncogenic role in glioblastoma is further manifested through its modulation of apoptotic signaling pathways." (PMID 38398118, 2024). "Overexpression of METTL3 in glioblastoma stem cells (GSCs) has been correlated with a poor prognosis for glioblastoma and its silencing in GSCs has been shown to reduce tumour growth in vivo." (PMID 38545841, 2024). "The characters of METTL3 in cancer stem cells of glioblastomas are somewhat contradictory in different publications." (PMID 38398118, 2024). "Glioblastoma progression can be stopped by METTL3 overexpression in tumor cells or by pharmacologically inhibiting FTO demethylase." (PMID 38937660, 2024). "In neurosphere assays of human glioblastoma cell lines, silencing METTL3 reduces the expression of glioblastoma reprogramming factors POU3F2, SOX2, SALL2, and OLIG2, and inhibits glioblastoma cell proliferation." (PMID 39473440, 2024). "METTL3 expression was also elevated in glioblastoma stem-like cells (GSCs) and was attenuated during differentiation." (PMID 37612540, 2023). "PDGF ligands stimulated early growth response 1 (EGR1) transcription to induce METTL3 to promote glioblastoma stem cells (GSC) proliferation and self-renewal." (PMID 36835633, 2023). "Among these diseases, there are few studies on the direct regulation of METTL3 on the occurrence and development of glioblastoma." (PMID 36970605, 2023). "Conversely, METTL3 facilitated cell survival by stabilizing the mRNA of SRY­box 2 (SOX2) in glioblastoma." (PMID 37919739, 2023). "METTL3 has been shown to maintain temozolomide resistance in glioblastoma cell lines and rodent models, suggesting the feasibility of using METTL3-inhibitors alongside current chemotherapy." (PMID 37444417, 2023). "In glioblastoma, METTL3 can promote the maintenance and radiation resistance of glioblastoma stem cells and inhibit their self-renewal and proliferation." (PMID 37519297, 2023). "METTL3 is up-regulated in human glioblastoma tissues and induces m6A modification by binding to SOX2 mRNA in 3′UTR." (PMID 37437245, 2023). "The existing studies suggest that METTL3 can promote the development of glioblastoma stem cells in the m6A modification pathway." (PMID 36970605, 2023). "In glioblastoma, the METTL3-METTL14 complex was discovered to be both tumor-promoting and tumor-suppressive." (PMID 37919739, 2023). "The highly cited literature expounded overexpression of METTL3 gene suppresses glioblastoma stem cells growth and self-renewal." (PMID 36970605, 2023). "The growth of murine glioblastoma can be decelerated or stagnated by silencing the METTL3 to inhibit the expression level of SOX2." (PMID 37437245, 2023). "In glioblastoma, METTL3 expression increased, and for METTL3-silenced glioma stem cells (GSCS), their radiosensitivity was enhanced and DNA repair was reduced." (PMID 35628460, 2022). "It is very interesting that METTL3, which is upregulated in glioblastoma cells, targets ADAR1 mRNA to stabilize their transcript and increase ADAR1 protein level." (PMID 36012529, 2022).
glioblastoma (continued). "In glioblastoma, downregulation of FTO or upregulation of METTL3 was involved in the poor prognosis of glioblastoma by promoting the proliferation and self-renewal of glioblastoma stem cells." (PMID 35814454, 2022). "Due to the upregulation of METTL3 in glioblastoma, a high level of m6A complicates the deaminase activity of ADAR1." (PMID 36012529, 2022). "m6A methylation and its enzyme METTL3 are upregulated in glioblastoma stem cells and HCC, and the high expression of METTL3 induces SOCS2 degradation by m6A methylation, thus promoting tumor cell growth and survival." (PMID 36401285, 2022). "A recent study has shown that ADAR1 is one of the targets of METTL3 and plays an oncogenic role in glioblastoma." (PMID 36077054, 2022). "METTL3 is also upregulated in glioblastoma, and silence of METTL3 inhibits the growth of glioma stem cells by downregulating POU3F2, SOX2, SALL2, OLIG2, and other glioma recombinant factors." (PMID 35571490, 2022). "It was shown earlier that METTL3-mediated m6A RNA modification is critical for glioblastoma stem cell maintenance and dedifferentiation of glioma cells." (PMID 36012529, 2022). "In a large number of glioblastoma samples, m6A-modified mRNA was found to be expressed in human glioma tissue, and the expression of METTL3 also showed a downward trend with the increase in malignancy grade." (PMID 35682599, 2022). "As an m6A writer, METTL3 regulated cancer initiation and progression, including glioblastoma, BC, HCC, leukemia, and other cancer cells." (PMID 36517820, 2022). "METTL3 knockdown dramatically facilitates glioblastoma stem cell growth, self-renewal, and tumor progression." (PMID 35474040, 2022). "METTL3 knockout promotes the growth and self-renewal of human glioblastoma stem cells (GSCs) and promotes GBM development." (PMID 36118889, 2022). "Firstly, we knocked down the expression of METTL3 using three different siRNAs against METTL3 in two glioblastoma cell lines (U87MG and U118MG)." (PMID 34589481, 2021). "Mechanistically, upregulated METTL3 maintained the activation of glioblastoma stem cell (GSC) through regulating the RNA editing enzyme and the YTHDF2-mediated RNA decay." (PMID 33879256, 2021). "These controversial discoveries suggest that the role of METTL3 in glioblastoma requires further studies based on large amount of tumor samples and well-designed experimental systems." (PMID 33718165, 2021). "METTL3 depletion affects the glioblastoma stem cell features via promoting nonsense‐mediated mRNA decay (NMD) of histone modifiers, such as EZH2." (PMID 34586728, 2021). "METTL3 is a methyltransferase, and glioblastoma stem cells have high levels of METTL3 with global m6A modification." (PMID 33673851, 2021). "METTL3 was also reported to be a tumor suppressor by regulating cell cycle and self-renewal in renal cell carcinoma and glioblastoma." (PMID 33648590, 2021). "CCK8 assay showed that METTL3 knockdown inhibits glioblastoma cell proliferation at 72 h after transfection." (PMID 34589481, 2021). "Another salient example lies in glioblastoma; METTL3/14 knockdown can promote tumorigenesis for glioblastoma stem cell (GSC) by decreasing m6A modification in the mRNA of the targeted oncogene ADAM metallopeptidase domain 19 (ADAM19)." (PMID 34895230, 2021). "Controversially, another two studies found that clinical aggressiveness of glioblastoma is related to increased expression of METTL3." (PMID 34113622, 2021). "METTL3 expression promoted radioresistance in glioma by promoting glioblastoma stem cell maintenance through m6A-mediated stabilization of SOX2, and subsequent METTL3 knockdown resulted in increased radiosensitivity." (PMID 33669361, 2021). "METTL3 promotes GSC stemness by enhancing SOX2 stability in glioblastoma, and METTL3 silencing inhibits tumor growth." (PMID 34113622, 2021). "Then, we modulated METTL3 expression (shMETTL3) in glioblastoma cells and we quantified the m6A-marked sites of ADAR1 by qRT-PCR." (PMID 33509238, 2021).
glioblastoma (continued). "YTHDC1 has been shown to promote m6A/METTL3-mediated tumor cell growth in glioblastoma (GBM) via regulation of nonsense-mediated mRNA decay (NMD) of serine- and arginine-rich splicing factors (SRSF)." (PMID 33922187, 2021). "METTL3 was reported to be overexpressed in glioblastoma, and with METTL3 as a tumor suppressor, overexpression of METTL3 can inhibit the growth and self-renewal of glioblastoma stem cells (GCS)." (PMID 32596151, 2020). "This work holds an undeniable value sustaining the protumoral role of METTL3-mediated mRNA methylation in glioblastoma." (PMID 32316617, 2020). "Previous studies indicated the role of METTL3 in the self‐renewal and tumorigenesis of glioblastoma stem cells." (PMID 33090698, 2020). "On the contrary, other studies also demonstrated that METTL3 played an suppressive role in endometrial cancer and glioblastoma." (PMID 32419773, 2020). "Intriguingly, reasons of m6A dysregulation in CSCs are different among various types of cancer, considering the roles of FTO, ALKBH5, and METTL3 in glioblastoma stem cells and of METTL14 and FTO in leukemia stem cells." (PMID 32676121, 2020). "In contrast, another report demonstrated that high expression of METTL3 in human glioblastoma tissues was a predictor of poor prognosis." (PMID 32850334, 2020). "Of clinical relevance is also the result about the reduced in vivotumorigenicity of U87 stem-like cells depleted of METTL3, together with the evidence of METTL3 mRNA and protein higher abundance in glioblastoma tissues compared to normal brain." (PMID 32316617, 2020). "The same group went further in its study of METTL3 role in glioblastoma stem cells by performing an integrated analysis of m6A-RIP (RNA immunoprecipitation) and total RNA-Seq of METTL3-silenced GSCs." (PMID 32316617, 2020). "In glioblastoma, overexpression of METTL3 was reported to be crucial in maintaining the stemness and dedifferentiation capability of glioblastoma stem cells (GSCs)." (PMID 32194861, 2020). "There is a correlation between the degree of m6A RNA methylation and the differentiation of GSCs and between the effect of METTL3 knockdown on in vitro self-renewal and in vivo tumourigenicity of glioblastoma in mice." (PMID 32943100, 2020). "For m6A methylases, METTL3 has been reported to promote the growth and tumorigenesis of human liver cancer cells, acute myeloid leukaemia cells and glioblastoma stem cells but also act as a tumor suppressor in renal cell carcinoma." (PMID 30953473, 2019). "As is the case of METTL3 in glioblastoma, METTL14 depletion facilitates the malignant phenotype, characterized by upregulated oncogenes such as ADAM19 and reduced expression of tumor suppressors such as CDKN2A." (PMID 31921664, 2019). "Comprehensive analysis of direct and indirect targets with RNA regulation post METTL3 silencing showed that it is indispensable for key glioblastoma-related oncogenic pathways such as NOTCH, NFκB, Wnt, c-Myc, and TGF-β." (PMID 30781903, 2019). "m6A modification in mRNA of glioblastoma stem cells regulates their capacity of self-renewal and tumorigenesis, with overexpression of writers (METTL3 and METTL14) and downregulation of erasers (FTO and ALKBH5) inhibiting tumor growth." (PMID 30428628, 2018). "METTL3 or METTL14 knockdown dramatically promotes human glioblastoma stem cell growth, self‐renewal and tumorigenesis." (PMID 29502358, 2018). "Recent studies found m6A-modifying enzymes Mettl3, Alkbh5, and Fto to be involved in regulating progression of glioblastoma, indicating that m6A epitranscriptomic regulation plays roles in the nervous system." (PMID 29855337, 2018). "Moreover, the inhibition of METTL3 can increase glioblastoma stem cell self-renewal by modulating m6A modification of adenine phosphoribosyltransferase (APNG) mRNAs, thereby increasing the sensitivity of glioblastoma multiforme to temozolomide." (PMID 40986143, 2025). "In summary, METTL3 plays a pivotal role in promoting glioblastoma progression." (PMID 41321637, 2025).
glioblastoma (continued). "Therefore, METTL3 couples with YTHDC1 to play a role in the anti-apoptosis of glioblastoma cells, partially mediated through the splicing modulation of BCL-X." (PMID 38398118, 2024). "Moreover, their RNA sequencing results revealed an enrichment of carcinogenesis-related pathways, such as apoptotic signaling pathways, among the set of m6A-regulated genes in METTL3-silenced glioblastoma cell lines." (PMID 38398118, 2024). "Furthermore, METTL3-mediated m6A modification was shown to promote stemness maintenance and radioresistance in glioma stem cells (GSCs), highlighting METTL3 as a promising therapeutic target in glioblastomas (GBMs)." (PMID 38355684, 2024). "U87 MG glioblastoma cells were subcutaneously implanted into wild‐type and Mettl3–lecKO mice." (PMID 39372388, 2024). "Targeting the promoting effect of METTL3 on glioblastoma or further exploring the influence of downstream molecules such as ADAR1 on the disease perhaps could open up a new field of epigenetics in glioblastoma." (PMID 36970605, 2023). "Besides AML and glioblastoma, oncogenic roles were also reported for METTL3 in multiple other cancer types." (PMID 37612540, 2023). "The role of METTL3 in glioblastoma could be a new research direction, and it is more likely to find new research results for scientists." (PMID 36970605, 2023). "Furthermore, we found that some studies showed an increase, and others a decrease in METTL3 expression in glioblastoma." (PMID 37189411, 2023). "Moreover, upregulation of METTL3 has also been observed in various other cancer types, including glioblastoma, lung, stomach, bladder, pancreas, and prostate cancers." (PMID 38012755, 2023). "Additionally, it is reported that METTL3-mediated m6A modification was significantly elevated in temozolomide (TMZ)-resistant glioblastoma cells." (PMID 35625706, 2022). "Knockdown of METTL3 inhibits the proliferation of glioblastoma cell lines." (PMID 36012529, 2022). "Thus, there is an important new interaction—METTL3/ADAR1/CDK2—as a potential target for glioblastoma therapy." (PMID 36012529, 2022). "Experimentally, METTL3 overexpression impaired the TMZ-sensitivity of glioblastoma cells, while METTL3 silencing or 3-deazaadenosine (DAA)-mediated total methylation inhibition improved the sensitivity of TMZ-resistant glioblastoma cells to TMZ in vitro and in vivo." (PMID 35625706, 2022). "For example, in the study of glioblastoma stem cells, researchers found that knocking out METTL3 could greatly promote the growth, self‐renewal and tumorigenesis of human glioblastoma stem cells." (PMID 34075693, 2021). "Low levels of METTL3 or METTL14, key components of the RNA methyltransferase complex, have been shown to reduce the expression of m6A-modified ADAM19 RNA, whereas high ADAM19 RNA expression in glioblastoma stem cells causes glioblastoma." (PMID 34136491, 2021). "METTL3 promotes self-renewal of glioblastoma stem cells to induce tumorigenesis." (PMID 34568001, 2021). "Furthermore, CCK8 assay showed that METTL3 knockdown inhibits glioblastoma cell proliferation at 72 h after transfection of siRNA (p < 0.05)." (PMID 34589481, 2021). "It was reported that METTL3 could participate in glioblastoma tumorigenesis by enhancing glioma stem-like cell (GSC) maintenance and radioresistance." (PMID 32175271, 2020). "METTL3 promotes tumour growth and predicts poor survival in patients with glioblastoma." (PMID 33029866, 2020). "At present, the role of METTL3 in the progression of glioblastoma is still controversial." (PMID 33029866, 2020). "Thus, the methylation activity of METTL3 is critical for the oncogenic role of this protein in glioblastoma." (PMID 32316617, 2020). "Additionally, Cui and colleagues reported that METTL3 downregulation significantly promoted the growth, self-renewal, and tumorigenesis of human glioblastoma stem cells, while METTL3 overexpression inhibited the growth and self-renewal of these cells." (PMID 32111180, 2020).